MIR6842 (microRNA 6842)
Synonyms: hsa-mir-6842
Gene: MicroRNA gene on chromosome 8 (27,433,370 to 27,433,434, forward strand). Ensembl gene ENSG00000273836.
Homologues: Orthologues: chimpanzee MIR6842 (100% identical).